TPD52L3 (TPD52 like 3)
Synonyms: hD55; NYD-SP25; D55; TPD55; NYDSP25
Tractability: No criterion of Open Targets' tractability assessment is met for any kind of drug.
Gene: Protein-coding gene on chromosome 9 (6,328,375 to 6,331,891, forward strand). Ensembl gene ENSG00000170777.
Gene Ontology:
Molecular function: protein binding
Cellular component: cytoplasm
Genetic constraint (gnomAD): Loss-of-function variants: 14 observed, 11.51 expected, observed/expected ratio (o/e) 1.22, 90% interval 0.8 to 1.8. The upper end of that interval is the gene's LOEUF score, 1.8, which puts it in group 6 of 6, group 1 being the genes least tolerant of losing a copy. Missense variants: 207 observed, 168.46 expected, observed/expected ratio (o/e) 1.23, 90% interval 1.1 to 1.38. Synonymous variants: 79 observed, 70.96 expected, observed/expected ratio (o/e) 1.11, 90% interval 0.93 to 1.34.
Homologues: Orthologues: chimpanzee TPD52L3 (91% identical), macaque TPD52L3 (86% identical), rabbit TPD52L3 (71% identical), pig TPD52L3 (68% identical), mouse Trpd52l3 (66% identical), rat Tpd52l3 (65% identical), dog TPD52L3 (62% identical), Caenorhabditis elegans F13E6.1 (30% identical), Drosophila melanogaster CG5174 (25% identical). Paralogues in human: TPD52L2 (54% identical), TPD52 (40% identical), TPD52L1 (40% identical).
Diseases named in the same sentence as TPD52L3 in open-access papers:
TPD52L3 is named in the same sentence as 5 diseases in open-access papers, as found by Europe PMC text mining. Sharing a sentence is not in itself a finding about the gene and the disease. The quoted sentences say what the papers report.
brain tumors (1 paper, 2021). "Other family members, such as TPD53 (also known as TPD52L1), TPD54 (TPD52L2), and TPD55 (TPD52L3), have been reported to be highly expressed in ovary, testis, colon, and prostate cancer, as well as in brain tumors, lymphoma, and leukemias." (PMID 34217360, 2021).
TPD52L3 also shares sentences with these, for which no sentence is quoted: cancer (1 paper); leukemia (1); lymphoma (1); prostate carcinoma (1).